RASA4 (RAS p21 protein activator 4)
Description:
Ca(2+)-dependent Ras GTPase-activating protein, that switches off the Ras-MAPK pathway following a stimulus that elevates intracellular calcium. Functions as an adaptor for Cdc42 and Rac1 during FcR-mediated phagocytosis.
Synonyms: CAPRI; GAPL; KIAA0538
Tractability: Antibody: UniProt places it where antibodies can reach, with high confidence; its Gene Ontology location is reachable by antibodies, with high confidence. PROTAC: ubiquitination databases record sites on it.
Gene: Protein-coding gene on chromosome 7 (102,579,646 to 102,616,756, reverse strand). Ensembl gene ENSG00000105808.
Subcellular location: Cytoplasm, cytosol; Cell membrane
Subcellular location (Human Protein Atlas): Vesicles; Cell Junctions
Pathways (Reactome):
Signal Transduction: Regulation of RAS by GAPs
Gene Ontology:
Molecular function: GTPase activator activity; phospholipid binding
Biological process: cellular response to calcium ion; negative regulation of GTPase activity; regulation of intracellular signal transduction; intracellular signal transduction; negative regulation of Ras protein signal transduction
Cellular component: cytosol; plasma membrane
Genetic constraint (gnomAD): Loss-of-function variants: 5 observed, 5.75 expected, observed/expected ratio (o/e) 0.87, 90% interval 0.45 to 1.7. That is too few expected variants to judge how well the gene tolerates losing a copy. Missense variants: 35 observed, 65.75 expected, observed/expected ratio (o/e) 0.53, 90% interval 0.41 to 0.71. Synonymous variants: 9 observed, 16.95 expected, observed/expected ratio (o/e) 0.53, 90% interval 0.32 to 0.93.
Homologues: Orthologues: macaque RASA4B (96% identical), guinea pig Rasa4b (89% identical), rat Rasa4 (87% identical), dog RASA4B (87% identical), mouse Rasa4 (86% identical), tropical clawed frog rasa4 (68% identical), zebrafish rasa4 (62% identical), Drosophila melanogaster raskol (28% identical), Drosophila melanogaster RasGAP1 (27% identical), Caenorhabditis elegans gap-2 (17% identical), Caenorhabditis elegans gap-1 (17% identical). Paralogues in human: RASA4B (99% identical), RASAL1 (49% identical), RASA3 (31% identical), RASA2 (30% identical), NF1 (27% identical), RASAL2 (23% identical), DAB2IP (22% identical), RASA1 (19% identical), RASAL3 (17% identical).
Diseases named in the same sentence as RASA4 in open-access papers:
RASA4 is named in the same sentence as 17 diseases in open-access papers, as found by Europe PMC text mining. Sharing a sentence is not in itself a finding about the gene and the disease. The quoted sentences say what the papers report.
triple-negative breast carcinoma (4 papers, 2021 to 2025). An invasive breast carcinoma which is negative for expression of estrogen receptor (ER), progesterone receptor (PR), and human epidermal growth factor receptor 2 (HER2). "For example, TRPC3 channel promotes the growth of human ovarian cancer cells, and it can modulate the growth and apoptosis resistance of triple negative breast cancer cells via the TRPC3/RASA4/MAPK signaling pathway." (PMID 35870973, 2022). "TRPC3 overexpression has been detected in triple-negative breast cancer cells, and its activation induces an RAS P21 protein activator 4-mitogen-activated protein kinase (RASA4-MAPK) signaling cascade that plays a crucial functional role in preserving proliferation and resistance to apoptosis." (PMID 37892239, 2023).
cervical cancer (2 papers, 2021 to 2022). A primary or metastatic malignant neoplasm involving the cervix. "Our findings indicated that RASA4 can inhibit the proliferation of cervical cancer cells by inactivating the HIFα signaling pathway, suggesting novel prospects for targeted therapy against CESC." (PMID 34752201, 2021). "Another study demonstrated that RAS p21 protein activator 4 (RASA4) could inhibit the proliferation of cervical cancer cells by inactivating the HIFα signaling pathway." (PMID 35038961, 2022).
gastric cancer (2 papers, 2021). A primary or metastatic malignant neoplasm involving the stomach. "Furthermore, several genes belonging to the Ras GTPase-activating protein (RasGAP) family, including RASA3 (P = 0.0005), RASA4 (P = 0.003), and RASAL3 (P = 0.0016), were identified with hypermethylated promotors in EBVaGCs compared with that in precursor lesions and other gastric cancers." (PMID 34493320, 2021).
glioma (2 papers, 2021 to 2024). A benign or malignant brain and spinal cord tumor that arises from glial cells (astrocytes, oligodendrocytes, ependymal cells). "Most causal genes underwent CNV in glioma samples, with AS3MT, DNA2, and SCDF1 being predominantly heterozygous deletion, while RASA4 and EGFR were predominantly heterozygous and homozygous amplification." (PMID 39722126, 2024). "Most causal genes underwent copy number variation (CNV) in glioma samples, with AS3MT, DNA2, and SCDF1 being predominantly heterozygous deletion, while RASA4 and EGFR were predominantly heterozygous and homozygous amplification." (PMID 39722126, 2024).
cervical squamous cell carcinoma (1 paper, 2021). A squamous cell carcinoma arising from the cervical epithelium. "However, the role of RASA4 in cervical squamous cell carcinoma (CESC) remains unclear." (PMID 34752201, 2021).
juvenile myelomonocytic leukemia (1 paper, 2021). A myelodysplastic/myeloproliferative neoplasm of childhood that is characterized by proliferation principally of the granulocytic and monocytic lineages. "Another prominent example of RASA4 is that RASA4 hypermethylation causes its downregulation in resistant juvenile myelomonocytic leukemia, which is associated with a grim prognosis." (PMID 34752201, 2021). "A recent investigation on resistant juvenile myelomonocytic leukemia revealed RASA4 deregulation in cancer tissues and dismal prognosis." (PMID 34752201, 2021).
tumor (4 papers, 2021 to 2023). "BALB/c mice were pre-treated subcutaneously with the RASA4-deficient C-33A cells to establish a human CC xenograft tumor model." (PMID 34752201, 2021). "In the present study, PCDH10 overexpression significantly decreased the expression of genes associated with tumor progression and metastasis, including EREG, MMP1, MMP9, TGFB1, RASA4, and CXCL8, in GC cells." (PMID 37147733, 2023). "RAS p21 protein activator 4 (RASA4) has been recognized as a Ca2+-promoted Ras–MAPK pathway suppressor that inhibits tumor growth." (PMID 34752201, 2021). "The CCK8 and colony assays were performed to assess the impact of RASA4 ectopic expression and gene inactivation on tumor cell proliferation." (PMID 34752201, 2021). "Taken together, these results indicate the tumor-suppressing role of RASA4 in CC malignancy." (PMID 34752201, 2021). "The importance of RANKL in the mechanism of tumor sensitivity is supported by the associated upregulation of RASA4 expression in non-sensitive tumors, as RASA4 controls RANKL expression by regulating its shedding." (PMID 34868026, 2021). "Considering the connection of Ca(2+) with RASA4 and HIF1α, we hypothesized that RASA4 may negatively regulate HIF1α signaling and suppress tumor growth." (PMID 34752201, 2021). "Therefore, our results strongly suggest that RASA4 acts as a tumor suppressor in CC progression." (PMID 34752201, 2021). "Our present results are thus consistent with previous findings suggesting that RASA4 may cooperatively interact with RAS and HIF-1α to inhibit HeLa cell proliferation and abrogate the cytotoxic T-lymphocytes’ ability to kill tumor cells." (PMID 34752201, 2021).
cancer (3 papers, 2016 to 2021). A tumor composed of atypical neoplastic, often pleomorphic cells that invade other tissues. "When exposed to the intracellular Ca(2+) overload condition, RASA4 can cause the conversion of Ras to the inactive status, resulting in the inactivation of Ras signaling events, which plays an important role in controlling the cell fate and inhibiting cancer progression." (PMID 34752201, 2021). "Studies have demonstrated that RASA4 deregulation in cancer contributes to RAS inactivation, thereby inhibiting the MAPK cascade." (PMID 34752201, 2021). "We found that 30 of these genes which included Nckap1l, Ncf1, Pla2g15, Unc93b1, Lrrc33, Rgs10, Gmfg, Rbm25, C3ar1, Ccdc88b, Fam105a, Gng11, Phc1, Rasa4, Dag1, Tyrobp, Tmsb4x, Cfp, Prkd1, Gp49a, Trem2, C1qc, Lyz2, Igfbp7, Rab30, Cxcl16, Egfl7, Ube2r2, Pltp, and Cfb, showed a relation with cancer." (PMID 32812032, 2020).
bacterial infection (1 paper, 2021). "This is consistent with previous reports identifying RASA4 as important for microbial immune responses to bacterial infection." (PMID 34094999, 2021).
RASA4 also shares sentences with these, for which no sentence is quoted: lung carcinoma (3 papers); breast carcinoma (1); infection (1); neurofibromatosis type 1 (1); pancreatic carcinoma (1); prostate carcinoma (1); small cell lung carcinoma (1); virus infection (1).